CHEK2 (checkpoint kinase 2)
Diseases named in the same sentence as CHEK2 in open-access papers (continued):
Sharing a sentence is not in itself a finding about the gene and the disease.
breast cancer (continued). "CHEK2 variant c.1100delC, found in case 1927, is a founder variant across Europe, while it is less common in southern Europe, including breast cancer patients of Greek ancestry (0.16%)." (PMID 39624521, 2024). "Individuals who have germline pathogenic variants (gPVs) in CHEK2 are at increased risk to develop breast cancer and likely other primary cancers." (PMID 38848470, 2024). "This specific CHEK2 variant was recently reported to confer a moderately increased risk for breast cancer." (PMID 38867252, 2024). "The PVs in high-risk (BRCA1, BRCA2, PALB2) or moderate-risk (ATM, CHEK2) genes mainly associated with breast cancer in women follow an autosomal dominant inheritance pattern." (PMID 38722431, 2024). "One of the loci associated with early-onset infertility is the frameshift mutation (c.1100delC) in the tumor-suppressor gene CHEK2, which is associated with a 32% lifetime risk for breast cancer." (PMID 39566493, 2024). "This is supported by the significantly increased frequency of pathogenic CHEK2 variants among individuals with a history of both thyroid and breast cancer compared to breast cancer alone." (PMID 38415346, 2024). "This provides an excellent setting to establish a cohort to ultimately study the impact of CHEK2 c.1100delC on cancer risk prediction and surveillance, breast cancer treatment and prognosis." (PMID 39384226, 2024). "Germline pathogenic variants in checkpoint kinase 2 (CHEK2) are associated with a moderately increased risk of breast cancer (BC)." (PMID 38091153, 2024). "Its essential roles in cellular regulation mean that inherited PVs of CHEK2 are linked to a heightened risk of developing breast cancer." (PMID 39624521, 2024). "Individuals heterozygous for germline pathogenic variants (gPVs) in CHEK2 have a low-to-moderate risk to develop breast cancer." (PMID 38848470, 2024). "Studies show that carriers with a family history of breast cancer are at 2–3 times greater risk when breast cancer is associated with the CHEK2 c.1100delC mutation." (PMID 38504328, 2024). "In total, we analyzed 8 breast cancers and 8 other CHEK2-deficient cancers [colorectal cancer (CRC) (n = 4), thyroid (n = 2), endometrial (n = 1), and urothelial (n = 1) cancer]." (PMID 38848470, 2024). "Significant excess risk for cancers of the breast, male genital organ, urinary tract and lymphoid, hematopoietic, and related tissues in CHEK2 heterozygotes in both MyCode and UKBB." (PMID 39371170, 2024). "Earlier, it was found that CHEK2*1100delC heterozygosity in women with BC was associated with early death, breast cancer-specific death, and increased risk of recurring BC." (PMID 39684352, 2024). "The pathogenic germline CHEK2 c.1100delC variant is the most prevalent breast cancer (BC) predisposition variant in the Netherlands." (PMID 38039887, 2024). "We found that CHEK2 is the only cell cycle checkpoint kinase gene that is more likely to be mutated in the germ line than somatically (threefold enrichment in ER+/HER2− breast cancer relative to ATM and >50-fold enrichment relative to ATR, P = 3.7 × 10−12)." (PMID 37390209, 2023). "One of these is CHEK2 c.1312 G > T, p.(Asp438Tyr) in the kinase domain of the protein, but due to its rarity its clinical significance for breast cancer predisposition has remained unclear." (PMID 36653541, 2023). "Debates on the impact of CHEK2 pathogenic mutations on breast cancer risk are ongoing, with emerging data to classify pathogenic mutations of CHEK2 in moderate to low-penetrant variants." (PMID 37239058, 2023).
breast cancer (continued). "In the group of 6755 patients with breast cancer diagnosed at age below 51, CHEK2 mutations were present in 10 of 52 (19,2%) breast-thyroid cancer patients and in 585 of 6703 (8,7%) breast cancer patients (OR 2.49; P = 0.01)." (PMID 37434214, 2023). "The Breast Cancer Association Consortium provided a unique resource of 963 carriers of this single CHEK2 variant to study this question in more detail." (PMID 36824750, 2023). "Recently, we reported that oophorectomy improves the 15-year survival of breast cancer patients with a CHEK2 mutation by about 15% and should be considered in the treatment of CHEK2 mutation-associated breast cancers." (PMID 37510234, 2023). "Contralateral breast cancer risk (hazard ratio) by treatment for first primary breast cancer and CHEK2 c.1100delC status." (PMID 37401034, 2023). "GGT of the CHEK2 gene yields appreciable frequencies of pathogenic or likely pathogenic (P/LP) germline variants in breast cancer or other patients with cancer." (PMID 37449874, 2023). "Germline pathogenic variants in CHEK2 confer moderately elevated breast cancer risk (odds ratio, OR ∼ 2.5), qualifying carriers for enhanced breast cancer screening." (PMID 37449874, 2023). "Another study found that germline CHEK2 mutations have a significant correlation with ovarian and breast cancer." (PMID 37965453, 2023). "Results from this overview analysis indicate that CHEK2 is the only cell cycle checkpoint kinase that robustly correlates with the evolution of a specific breast cancer subtype, i.e., ER+/HER2−, when mutated." (PMID 37390209, 2023). "CHEK2 is a tumor suppressor gene conferring a predisposition to sarcoma, breast cancer, and brain tumors." (PMID 38136276, 2023). "The patient with CHEK2 variant (rs375507194) passed away due to progression of her breast cancer after 2 years." (PMID 37277882, 2023). "CHEK2 mutation-associated breast tumors are more likely to be estrogen receptor (ER)-positive than sporadic breast cancers, and patients with breast cancer who carry a CHEK2 mutation respond well to tamoxifen." (PMID 37510234, 2023). "Out of the 21 hereditary breast-cancer-related genes, (likely) pathogenic germline mutations were only present in CHEK2 (two patients) and ATM (one patient)." (PMID 37239898, 2023). "Certain variants in the CHEK2 gene (I157T and c.1100delC) are associated with higher risk for breast cancer." (PMID 37781190, 2023). "This geographical enrichment provides an opportunity to test the association of CHEK2 p.(Asp438Tyr) with breast cancer susceptibility at the population level." (PMID 36653541, 2023). "We also find that breast cancer patients with CHEK2 mutations appear resistant to endocrine monotherapy, which targets the ER signaling pathway, despite their cancer being highly PR+." (PMID 37390209, 2023). "A recent study has shown poorer clinical outcomes for breast cancer patients diagnosed with invasive, early-onset breast cancer who carry a CHEK2 pathogenic variant." (PMID 36845387, 2023). "Carriers of functionally impaired missense variants accounted for 0.5% of patients with breast cancer and were associated with a moderate risk similar to that of truncating CHEK2 variants." (PMID 37449874, 2023). "To conclude, the current results indicate that the classification of CHEK2 p.(Asp438Tyr) variant can be changed from VUS to likely benign for breast cancer." (PMID 36653541, 2023). "The most predominant pathogenic variant in several populations in this gene is c.1100delC, which accounts for most of the truncating CHEK2 variants and is associated with breast cancer with 2.3 relative risk." (PMID 36653541, 2023). "Frequency of CHEK2 missense variants in our study was 3.4% in patients with breast cancer and 2.2% in controls (OR, 1.52; 95% CI, 1.43–1.61)." (PMID 37449874, 2023).
breast cancer (continued). "We observed a high frequency for CHEK2 variants, the most frequent moderate-risk breast cancer predisposition gene." (PMID 37239058, 2023). "The most frequent pathogenic CHEK2 variant is 1100delC, a loss-of-function mutation conferring 2-fold risk for breast cancer." (PMID 36653541, 2023). "Contralateral breast cancer risk (hazard ratio) by treatment for first primary BC and CHEK2 c.1100delC status in ER‐positive BC patients." (PMID 37401034, 2023). "Large and multiple independent epidemiological studies demonstrate association of germline variants in ATM and CHEK2 with incidence of ER+/HER2− breast cancer." (PMID 37390209, 2023). "The founder CHEK2 mutation c.1100delC is a moderate-risk variant in breast cancer, whereas the p.I157T is a low-risk variant." (PMID 39524544, 2023). "Biallelic loss of CHEK2 has been associated with significantly higher breast cancer risks than heterozygote carriership in earlier studies, and indeed, bilateral breast cancer was seen in six out of the 7 women with two PVs in CHEK2." (PMID 37563628, 2023). "This is supported by studies showing variable rates of somatic mutations or loss of heterozygosity of the remaining CHEK2 allele in adult breast cancer patients." (PMID 36980535, 2023). "The risk is independent on the age of breast cancer diagnosis, type of CHEK2 mutation and is the highest during 5 years after breast cancer diagnosis (SIR 9.6)." (PMID 37434214, 2023). "Carriers of PALB2, BARD1, RAD51C, RAD51D, ATM, and CHEK2 are at higher risk of breast cancer as well." (PMID 37458761, 2023). "Two recent large studies demonstrated that CHEK2 is the second most frequently altered breast cancer predisposition gene among patients of European descent, surpassed by BRCA2 and followed by BRCA1 in frequency of germline pathogenic variants." (PMID 37449874, 2023). "The predisposition toward developing ER+/HER2− breast cancer from cells with CHEK2 mutations indicated the potential involvement of germline variants." (PMID 37390209, 2023). "We find that women who are carriers of deleterious, germline variants in CHEK2 are predisposed to the incidence of premenopausal ER+/HER2− breast cancer." (PMID 37390209, 2023). "CHEK2 mutations confer about a 3- to 5-fold increased risk of breast cancer in a woman depending on her family history of breast cancer." (PMID 37510234, 2023). "Because the increased breast cancer risk, CHEK2 analysis has become a routine component of germline gene panels for identification of individuals at risk." (PMID 37449874, 2023). "Here, we tested the prevalence of CHEK2 p.(Asp438Tyr) allele showing enrichment in the Northern Finnish population, in a total of 2284 breast cancer patients from this geographical region." (PMID 36653541, 2023). "As a more direct test of the impact of the postmenopausal mammary environment on CHEK2 mutation–induced breast cancer evolution, we used the 4-vinylcyclohexene diepoxide (VCD) model to induce menopause in heterozygous and homozygous mutant, female mice." (PMID 37390209, 2023). "For CHEK2, several rare missense variants have been reported and generally these have been estimated to confer lower breast cancer risk than protein truncating variants." (PMID 36653541, 2023). "Several other CHEK2 alleles have been discovered in breast cancer families, but the majority of these are rare, complicating the risk estimations and the interpretations of their clinical significance." (PMID 36653541, 2023). "In the group of 4114 patients with breast cancer diagnosed at age above 50, CHEK2 mutations were present in 8 of 41 (19,5%) breast-thyroid cancer patients and in 324 of 4073 (8,0%) breast cancer patients (OR 2.81; P = 0.01)." (PMID 37434214, 2023). "Regarding moderate-risk breast cancer susceptibility genes, CHEK2 was the most frequently mutated gene in our population." (PMID 38136276, 2023).
breast cancer (continued). "Breast cancer (BC) patients with a germline CHEK2 c.1100delC variant have an increased risk of contralateral BC (CBC) and worse BC-specific survival (BCSS) compared to non-carriers." (PMID 36824750, 2023). "Inherited mutations in the CHEK2 gene have been associated with an increased lifetime risk of developing breast cancer (BC)." (PMID 38476463, 2023). "The CHEK2 c.1100delC mutation, leading to premature translation termination, was discovered to be the first moderate-risk breast cancer (BC) susceptibility allele in 2002." (PMID 37161532, 2023). "Clinically, CHEK2 deletion has previously been shown to be associated with breast cancers via a combined assay using NGS and MPLA." (PMID 35406559, 2022). "For other germline risk variants (e.g., ATM serine/threonine kinase [ATM], partner and localizer of BRCA2 [PALB2], and checkpoint kinase 2 [CHEK2]), susceptibility to breast cancer has been estimated to account for less than 50% of cases." (PMID 35025760, 2022). "Heterozygous loss-of-function germline pathogenic variants in CHEK2 are associated with an increased risk for breast cancer with a lifetime risk of 25–39%." (PMID 35281821, 2022). "Germline mutations in PALB2, ATM, and CHEK2 are also associated with breast cancer risks as high as those associated with BRCA1/2 mutations and are often referred to as BRCA-like breast cancer." (PMID 35884530, 2022). "For instance, in addition to a known association with breast cancer, we found variants in CHEK2 to be associated with the risk of colorectal and thyroid cancers, uterine leiomyoma, benign meningeal tumours and ovarian cysts." (PMID 35197637, 2022). "The CHEK2*1100delC variant is a well-established breast cancer risk variant in European populations and was also associated with prostate cancer." (PMID 35295987, 2022). "The CHEK2 1100delC is also the only CHEK2 allelic variant known to be associated with breast cancer risk factors as well as early death from breast cancer, ER‐positive breast cancer, and a diagnosis of a second breast primary." (PMID 35040284, 2022). "CHEK2 (also referred to as CHK2) loss of function has been firmly associated with breast cancer development." (PMID 36440216, 2022). "PVs of ATM and CHEK2 confers greater than 30% lifetime risk for breast cancer, but lower than that of BRCA1 and BRCA2, thus are regarded as moderate-high risk." (PMID 35323371, 2022). "Among women with a CHEK2 mutation and breast cancer, the relative risk increases from three-fold to nine-fold." (PMID 35205705, 2022). "We report the case of a breast cancer survivor, diagnosed with an underlying CHEK2 c.1100delC heterozygosity, who developed a papillary thyroid cancer 5 years later." (PMID 35101071, 2022). "PALB2 (1.2%) was the most commonly mutated gene other than BRCA1/2 in Chinese breast cancer patients, while CHEK2 (2.82%), ATM (1.06%), and PALB2 (0.87%) were the most commonly mutated genes other than BRCA1/2 in European populations." (PMID 35494038, 2022). "ATM and CHEK2 are examples of moderate-penetrance genes with lower lifetime risk of developing breast cancer as compared to the high-penetrance genes BRCA1 and BRCA2, and these moderate-penetrance genes account for around 6% of HBC." (PMID 35625741, 2022). "Among those with a pathogenic variant in CHEK2, there were 50% with a family history of breast cancer in contrast to those with ATM where there were only 28.6% with a family history of breast cancer." (PMID 35040284, 2022). "Seven of the eleven patients (63%) patients with both thyroid and breast cancer had a CHEK2 mutation, compared to 16% (73/468) of the thyroid cancer patients without breast cancer (p < 0.001)." (PMID 35205705, 2022).
breast cancer (continued). "The use of genome-wide association studies (GWAS) in breast cancer families has allowed the identification of genes that are characterized by incomplete penetrance, e.g., CHEK2 and ATM." (PMID 35625741, 2022). "Two individuals had pathogenic variants in CHEK2 (c.1427C > T p.Thr476Met and c.1100delC p.Thr367fs), which is known to be associated with a predisposition to mainly breast cancers, and other cancers including CRC." (PMID 35128723, 2022). "The frequencies in other breast cancer susceptibility genes such as CHEK2 and ATM are lower in East Asian populations than that of European populations." (PMID 35494038, 2022). "Another genetic variation associated with intermediate dangers of breast cancer and a 20%–40% lifetime chance of getting breast cancer includes the CHEK2, ATM, and PALB2 genes involved in the DNA repair process." (PMID 35762299, 2022). "Considering the increased risk of contralateral breast cancer associated with this germline CHEK2 mutation, the patient opted for a preventive contralateral mastectomy with bilateral breast reconstruction." (PMID 35101071, 2022). "In individuals with a family history of breast cancer, young onset breast cancer, and ovarian cancer, the most common pathogenic variant was in CHEK2." (PMID 35040284, 2022). "We have estimated that a CHEK2 mutation increases the risk of breast cancer by 2.5 times and the risk of thyroid cancer by 3.3 times." (PMID 35205705, 2022). "In Poland, following a diagnosis of breast cancer, the risk of thyroid cancer is increased four times, but is increased nine times in women who carry a CHEK2 mutation." (PMID 35205705, 2022). "It is possible that the genetic background (e.g., SNPs) that predispose CHEK2 carriers to breast cancer also predispose them to thyroid cancer." (PMID 35205705, 2022). "Of individuals with a CHEK2 pathogenic variant, 40% had breast cancer, 3% had ovarian cancer, and 4.6% had colon cancer." (PMID 35040284, 2022). "The CHEK2 mutation 1100delC and CHEK2 I157T mutations associated with hereditary breast cancer are the two most common CHEK2 mutations identified in NSCLC." (PMID 36061833, 2022). "In a systematic review by Liang, CHEK2*1100delC was associated with an increased risk of breast cancer in both men and women." (PMID 35885460, 2022). "For 925 probands with a diagnosis of breast cancer, the most commonly occurring pathogenic variant was in CHEK2 (n = 26)." (PMID 35040284, 2022). "All 66 CHEK2 PV carriers received their test result in-person at the genetics department and were counseled about breast cancer risk, surveillance strategies and the implications for their family members." (PMID 33468213, 2021). "Case-control studies of breast cancer have consistently shown that pathogenic variants in CHEK2 are associated with about a 3-fold increased risk of breast cancer." (PMID 33803639, 2021). "First, the same genes were involved, and (with the exception of CHEK2) in similar proportions, in inherited predisposition to breast cancer in AA and EA women." (PMID 33479248, 2021). "This work found that there were CHEK2 rare variants (in addition to CHEK2 c.1100delC) associated with increased breast cancer risk and a substantial proportion of these were missense variants." (PMID 33803639, 2021). "In conclusion, we recommend that a molecular test for BRCA1, BRCA2, PALB2 and CHEK2 recurrent mutations should be offered to male breast cancer patients in Poland." (PMID 34461861, 2021). "As CHEK2 is now part of a multigene panel for testing of breast cancer patients, more accurate risk estimates for breast cancer and other phenotypic information will become available in the near future." (PMID 33468213, 2021).